AR (androgen receptor)
Diseases named in the same sentence as AR in open-access papers (continued):
Sharing a sentence is not in itself a finding about the gene and the disease.
cancer (continued). "In the context of the IntClusts, most of the AR-driven Metabric tumors reside in IntClust4-, which consists of ER- tumors with favorable outcome, and in IntClust5, which captures most of HER2-amplified cancers regardless of ER status." (PMID 29382369, 2018). "This, byitself, can activate the AR by the law of mass action, but testosterone is not thephysiologic ligand as it is required to be converted to dihydroxytestosterone (DHT) in theprostate cancer cell." (PMID 29162647, 2018). "This suggests that ADT, especially when combined with cancer immunotherapy, may also provide therapeutic efficacy in TNBC patients who have the added negative prognostic indicator of being AR-." (PMID 27015557, 2016). "Without AR signaling, the fibroblast-derived ECM loses the capacity to promote attachment of both myofibroblasts and cancer cells, is less able to prevent cell-matrix disruption, and is less likely to impede cancer cell invasion." (PMID 25965833, 2015). "We noted that ectopic expression of FKBP5 resulted in moderate increase of AR in SKOV3 cells, whereas no significant increase of AR was detected in HEK293T cells, suggesting the possibility that higher survival signals may be present in cancer cells." (PMID 25460502, 2014). "Moreover, a similar high density-induced increase in the level of NED markers was detected using the AR-negative prostate cell line BPH-1 and its tumorigenic derivative CAFTD03, as well as the cancer cell lines DU-145 and PC3." (PMID 24884804, 2014). "Additionally, some researchers suggest that an apocrine phenotype and AR expression are essential for SDC diagnosis, proposing that salivary malignancies not meeting these criteria could be reclassified as different cancer subtypes." (PMID 39518333, 2024). "Other studies suggest that apocrine phenotype and AR expression are requisites for diagnosis of SDC, proposing that salivary malignancies that do not fit these criteria may be reclassified as alternative cancer subtypes." (PMID 38539538, 2024). "Mechanistically, in the absence of stromal AR signaling, the fibroblast-derived extra-cellular matrix (ECM) was shown to have a decreased capacity to promote attachment of both myofibroblasts and cancer cells, and was less likely to impede cancer cell invasion." (PMID 29210989, 2017). "Collectively, both ligand-dependent full-length AR (AR-FL) and AR-Vs mediate distinct transcriptional programs in CRPC21, 22, 23, but AR inhibitors currently in clinical use all target the LBD, and thus would not overcome cancer cell resistance driven by constitutively active AR-Vs." (PMID 27959342, 2016). "In four cases (AKT3, AR, MAPK1, and CTNNB1), we could observe a significant negative correlation in normal tissue, which was either non-significant or was significantly positive in cancer." (PMID 20920310, 2010). "However, in the aggressive AR-negative CRPC cells, upregulation of VEGFA could drive expression of Slug through the VEGFA/VEGFR2 autocrine signaling axis in an AR-independent manner, which promotes cancer cell survival and positively influence PCa progression." (PMID 32198489, 2020). "The similar expression pattern of AR in males verses females PTC in our study could not provide further insight to explain why the rates of extrathyroidal extension, lymph node metastasis, higher cancer stage and distant metastasis were found to be higher in men than in women with PTC." (PMID 32365531, 2020). "Therefore, our data suggest that regulating AR activity indirectly through FKBP52 either by ID4‐ or by FKBP52‐specific inhibitors such as MJC13 would be a valuable pharmacological tool for selectively attenuating persistent AR activity in CRPC, irrespective of hormonal milieu of the cancer." (PMID 28252832, 2017).
cancer (continued). "However, it is accepted that the TRA-1-60/CD151/CD166+VE stem cell may have arisen from a cell of origin for cancer that lacks AR, as in our study we did identify a very small fraction (19%) of α2β1HI CD133+VE cells lacking AR expression (0.0002% of the total epithelium)." (PMID 23145034, 2012).
adenocarcinoma (217 papers, 2006 to 2026). A common cancer characterized by the presence of malignant glandular cells. "We also detected an aberrant gain of a host of AR+ adenocarcinoma-associated TFs that were recently identified in other murine PCa models." (PMID 40570057, 2025). "All the patients in our matched study had adenocarcinoma at the time of diagnosis, suggesting that loss of AR expression emerges over time due to treatment pressure." (PMID 39286979, 2024). "t-NEPC is mainly caused by lineage plasticity transformation of adenocarcinoma after long-term androgen deprivation therapy or AR signaling inhibitor (ARSI) treatment, such as enzalutamide." (PMID 39103353, 2024). "Recent studies have implicated that the transdifferentiation of adenocarcinoma into treatment-emergent neuroendocrine PCa (t-NEPC) is a critical mechanism of drug resistance after treatment with the second generation AR antagonists." (PMID 37563661, 2023). "Continuously evolving acquired resistance mechanisms include frequent AR mutations and structural genomic alterations that drive an AR-positive prostate cancer (ARPC) adenocarcinoma phenotype." (PMID 37725435, 2023). "On the other hand, adenocarcinoma had higher luminal keratin and AR expression with low expression of NE-associated genes (represented as Krt8-high:Syp-low: AR-high)." (PMID 38168280, 2023). "As expected, alterations of the AR were common in PDXs of castrate-resistant adenocarcinoma, including amplifications, mutations, and structural rearrangements." (PMID 34413304, 2021). "The proposed mechanism for this progression involves an initially AR+ adenocarcinoma (ARPC) “losing” its luminal cell differentiation via the loss of AR activity." (PMID 33724955, 2021). "It is clear that most NEPC lack AR and NED can result in a loss of AR in the adenocarcinoma (at least some of NED tumors)." (PMID 27542219, 2016). "This study was undertaken to evaluate the diagnostic significance of AR expression in adenocarcinoma of breast and other morphologically similar adenocarcinomas." (PMID 17020615, 2006). "Evolving data have demonstrated differing HME patterns in CRPC adenocarcinomas compared to neuroendocrine and other atypical AR-independent PCs that can arise after treatment with ARSIs." (PMID 41601922, 2026). "CRPC adenocarcinomas typically retain dependence and expression of the AR and exhibit elevated activity of AR-target genes." (PMID 41601922, 2026). "NKX2–1 (another NEPC marker) also showed strong activity, while the adenocarcinoma lineage transcription factors AR and NKX 3.1 indicated far less inferred transcriptional activity." (PMID 41542660, 2026). "These morphologically distinct metastases displayed varying patterns of molecular phenotypes: The cribriform adenocarcinoma in the prostate was AR+/NE–, whereas the bone lesion was AR–/NE–." (PMID 40493417, 2025). "The PSA level of 137 ng/mL is atypically high for pure neuroendocrine prostate cancer and supports the predominance of an AR-driven adenocarcinoma clone." (PMID 40949061, 2025). "We recently found that REV-ERBα facilitates FOXA1 chromatin occupancy at non-AR target genes in ARSI-sensitive adenocarcinomas." (PMID 41231955, 2025). "Our findings that BRD4 in NEPC primarily controls the LP drivers and gene programs are in stark contrast to the fact that in CRPC adenocarcinomas BRD4 controls primarily AR signaling." (PMID 40370549, 2025). "This process allows AR-dependent adenocarcinoma cells to transition to AR-independent phenotypes, such as t-NEPC." (PMID 40361461, 2025).
adenocarcinoma (continued). "Specifically, the AD‐TFs list includes 21 previously reported TFs in adenocarcinoma, with AR occupying the top rank." (PMID 40091506, 2025). "ARSI withdrawal can reverse ARSI-resistant cells to an AR-driven adenocarcinoma state and induce transcriptional reprogramming, due to restored AR canonical function (13, 43, –45)." (PMID 41231955, 2025). "Most of the PCs are adenocarcinomas with glandular initiation and are characterized by the expression of the AR and PSA markers." (PMID 41225814, 2025). "In NEPC, heightened ER stress not only supports cell survival under metabolic duress but also promotes the transition from an androgen-dependent adenocarcinoma to an androgen receptor (AR)-independent neuroendocrine phenotype." (PMID 41198652, 2025). "Rather, nearly every focus showed strong enrichment for genes in the AR-dependent adenocarcinoma gene group, which included AR, NKX3-1, and KLK3." (PMID 40906535, 2025). "The effects of PCE on AR-mediated signaling were further demonstrated in the human prostate cell line LNCaP, which is an androgen- and estrogen-sensitive adenocarcinoma." (PMID 39830338, 2024). "Lineage plasticity mediates resistance to androgen receptor pathway inhibitors (ARPIs) and progression from adenocarcinoma to neuroendocrine prostate cancer (NEPC), a highly aggressive and poorly understood subtype." (PMID 39470735, 2024). "The 10 CRPC adenocarcinoma GRNs broadly separated based on activity of the AR regulon, the dominant oncogenic pathway in CRPC." (PMID 38645034, 2024). "The most frequent PCa tumors are adenocarcinomas characterized by the expression of androgen receptor (AR) and prostate-specific antigen (PSA)." (PMID 38542079, 2024). "The 10 CRPC adenocarcinoma GRNs broadly separated based on the activity of the AR regulon, the dominant oncogenic pathway in CRPC." (PMID 38968122, 2024). "These new models are highlighted to represent the most important PCa subtypes, such as AR-driven (AR+) adenocarcinoma, AR-independent neuroendocrine positive (AR− NE+), or double-negative (AR− NE−) PCa." (PMID 38256166, 2024). "The first model suggests that resident neuroendocrine cells, before initiation of endocrine therapies, represent a minority of cells as they are outgrown by the AR-positive adenocarcinoma cells." (PMID 39195285, 2024). "Treatment-induced neuroendocrine prostate cancer (t-NEPC) often arises from adenocarcinoma via lineage plasticity in response to androgen receptor signaling inhibitors, such as enzalutamide." (PMID 38585965, 2024). "PCs most commonly are AR-expressing adenocarcinomas whereby an altered AR-driven transcriptional program results in malignant features." (PMID 38337427, 2024). "AR-positive adenocarcinoma cell lines including LNCaP and LNCaP-abl, responded to 5μM tazemetostat treatment over 6 days." (PMID 38405800, 2024). "Increasing evidence supports that lineage reprogramming from adenocarcinoma, which is AR dependent, to the neuroendocrine cell type that typically lacks AR signaling, acts as a mechanism of resistance manifested by NEPC." (PMID 38543137, 2024). "This phenomenon is common in PC cells that become resistant to ADT, when the cells lose characteristic adenocarcinoma histology and adapt to express neuroendocrine features and reduced AR activity." (PMID 38337427, 2024). "Many studies provided evidence that ARPIs stimulated the evolution of AR-independent mechanisms to fight the survival pressure, despite the initial blocking of luminal adenocarcinoma growth." (PMID 37385990, 2023). "Unlike the C4-2B cells the activation of NFAT:AP-1 would suggest the molecular response of NEPC cells to fimepinostat treatment differs from that of AR-positive adenocarcinoma." (PMID 37823778, 2023).
adenocarcinoma (continued). "Similar results were obtained with TRAMP-C2 cells and, more recently, in an AR+/PDX adenocarcinoma model (NSG-TM00298) and also with VCaP cells, which also convert from AS to AI after ADT, suggesting that this is likely a general response of AS PCa cells." (PMID 37446279, 2023). "CRPC usually remains an AR-dependent adenocarcinoma, but about 20% of the time, plasticity to other differentiated cell types is observed, including the expression of a neuroendocrine-lineage phenotype." (PMID 37183816, 2023). "We did this using the LNCaP and LNCaP-AR models of human adenocarcinoma, as these cells retain AR pathway activity with LNCaP-AR modified to overexpress AR." (PMID 36724278, 2023). "Newer functional analyses have demonstrated that NEPC typically originates from an AR-positive adenocarcinoma through transdifferentiation." (PMID 37446279, 2023). "We selected six PDXs with different phenotypes and genomic features 23, including three androgen receptor (AR)-positive adenocarcinomas and three AR-null tumors that express neuroendocrine markers, with a range of LeY expression." (PMID 37660083, 2023). "In general, expression of PSCA, PSMA and STEAP-1 is limited to AR-positive adenocarcinoma tumors and is rarely detected in AR-null or neuroendocrine prostate cancer, limiting their clinical application." (PMID 37660083, 2023). "LNCaP-NK1R and 22Rv1-NK1R demonstrated significant expression of NE marker CgA and ENO2 as well as the NE-related gene while the level of adenocarcinoma marker AR and PSA reduced." (PMID 37385990, 2023). "To identify the enzymes responsible for C4S upregulation in AR-indifferent CRPC, we interrogated RNA-Seq data obtained from the LTN331/LTN331R PDX trans-differentiation model during progression from adenocarcinoma to AR-independent NEPC." (PMID 35963852, 2022). "Partial neuroendocrine features (positive synaptophysin expression with maintained AR expression and an adenocarcinoma morphology) were noted in primary PCa from one patient (Patient 7) and in the metastasis of another patient (Patient 6)." (PMID 35220606, 2022). "Examination of 429 mCRPC patients revealed high AR signaling, mostly in adenocarcinomas and low AR signaling in samples with neuroendocrine histologic features." (PMID 35682963, 2022). "WLS is repressed by the AR in adenocarcinoma, but is increasingly expressed upon AR inhibition and t-NEPC transdifferentiation." (PMID 35109899, 2022). "Before initiation of ADT and NHA, these cells remain small in number as they are outgrown by the AR-positive adenocarcinoma cells." (PMID 35109899, 2022). "In healthy tissue or low-grade adenocarcinoma, AR represses SOX2 and maintains the differentiated state." (PMID 35109899, 2022). "Though NEPC can rarely arise de novo, more commonly, it arises from adenocarcinoma in response to selection pressure for AR-independent cells from treatment with AR signaling inhibitors via lineage plasticity and NE differentiation." (PMID 35582526, 2022). "Of 35 LuCaP PDX samples analyzed in this study, 11 tumors represented AR-null, and 21 represented the adenocarcinoma AR-positive CRPC subtype." (PMID 35406510, 2022). "AR‐positive adenocarcinomas were seen in both control and Phf8 knockout TRAMP mice at week 25 (data not shown)." (PMID 33009820, 2021). "The KIT expression was found to be weak in two samples and moderate in one sample, AR was moderately expressed in both patients with adenocarcinoma." (PMID 33296026, 2021). "The first three are de novo NEPC while NED originated from the trans-differentiation of adenocarcinoma during the process of resistance to ATD or androgen receptor pathway inhibitors (ARPIs) treatment." (PMID 34956090, 2021).
adenocarcinoma (continued). "The cellular heterogeneity and the molecular evolution during the progression from AR-positive adenocarcinoma to AR-negative NEPC has yet to be characterized." (PMID 34099734, 2021). "In fact, 40% of tumors that harbor both these two genetic alterations are classified as AR-active adenocarcinomas." (PMID 33420371, 2021). "Similar to the UW and SU2C mCRPC cohorts, transcriptome analysis revealed that AR-active adenocarcinoma PDX models had negligible MET and RET transcript expression, whereas 3 of 4 SCNPC PDX models and the NCI-H660 cell line had robust MET and RET expression." (PMID 33471819, 2021). "PRNCre allograft growth rate was slightly reduced following castration which is likely due to the fact that the tumors were heterogeneous with a component of AR-responsive adenocarcinoma." (PMID 34099734, 2021). "PC cells try to escape the inhibition of the AR pathway and transform from AR-driven adenocarcinoma to t-NEPC." (PMID 33921329, 2021). "To further confirm our H&E results, we conducted immunostaining for the adenocarcinoma marker AR and the NEPC markers SYP and CD56." (PMID 33009820, 2021). "UMAP analysis of scRNA-seq separated PDX 224R into 3 adenocarcinoma clusters and 5 neuroendocrine clusters, which varied in AR and NCAM1 (CD56) expression, and enrichment of NE and AR signatures." (PMID 34413304, 2021). "Among the adenocarcinomas, all PDXs are AR+, except 201.2A and 201.2A-Cx, which lack the AR but express CD5621." (PMID 34413304, 2021). "More recent functional studies have demonstrated that NEPC typically arises from AR-positive conventional adenocarcinoma through a transdifferentiation process." (PMID 33420371, 2021). "One of the RNA splicing factor, RNA splicing factor serine/arginine repetitive matrix 4, SRRM4, was recently identified as a strong stimulator of adenocarcinoma cells to express NEPC biomarkers under androgen receptor pathway inhibition." (PMID 33572108, 2021). "The UMAP for PDX287R also had multiple clusters of adenocarcinoma cells, with varying enrichment of AR and proliferative signatures." (PMID 34413304, 2021). "Similar results were obtained with TRAMP-C2 cells, and more recently in a AR+/PDX adenocarcinoma model (NSG-TM00298)." (PMID 33297404, 2020). "In contrast to the CRPC-adenocarcinoma patients, CRPC-NE patients showed reduced frequency of genomic alterations associated with androgen receptor (AR), indicating the selection of AR-independent clonal subpopulation during NEPC progression." (PMID 32754615, 2020). "Molecular characterization showed that this line expressed hallmarks of adenocarcinoma and is positive for AR and luminal cytokeratin (CK8)." (PMID 31839878, 2019). "Results from the screening of libraries constructed from the PC-3 line, as a model of metastatic AR-independent PCa, and of libraries obtained from PCa adenocarcinoma primary tumor are presented." (PMID 31694235, 2019). "Both SDC and adenocarcinoma can express the AR at varying rates, 70–100% of SDC and 21% of adenocarcinoma." (PMID 31428578, 2019). "Because high‐grade adenocarcinoma responded well to androgen receptor‐targeted therapies, the survival rate was better in patients with high‐grade adenocarcinoma than patients with SCC." (PMID 31518071, 2019). "The majority of primary PCas are adenocarcinomas expressing the androgen receptor (AR), a nuclear steroid hormone receptor critically involved in PCa development and progression." (PMID 29808619, 2018). "Decreased AR levels and AR-dependent signaling in various ganetespib-treated LuCaP adenocarcinoma models likely play a role in growth inhibition." (PMID 30467317, 2018). "There is a strong relationship between alterations in AR (both mRNA and protein) levels and the progression of PCa adenocarcinoma to NEPC." (PMID 29980692, 2018).